TLR7 (toll like receptor 7)
Diseases named in the same sentence as TLR7 in open-access papers (continued):
Sharing a sentence is not in itself a finding about the gene and the disease.
lupus (continued). "Taken account that IL-17a is a key factor contributing to endothelial dysfunction in this TLR7-driven lupus autoimmunity model, we next examined the changes brought by the antibiotics on the observed SLE-linked endothelial dysfunction." (PMID 34573058, 2021). "Overexpression of TLR7 in mice accelerates the development of SLE, whereas deficiency of TLR7 in lupus-prone mice ameliorates the phenotype." (PMID 32708595, 2020). "Aberrant activation of TLR7 has been implicated in several autoimmune diseases including systemic lupus erythematosus (SLE)." (PMID 33060576, 2020). "Studies in mouse models of spontaneous lupus also showed disease dependency on multiple predisposing genes, with the contribution of few higher impact accelerator genes in some strains, such as the Tlr7 gene duplication leading to increased TLR7 responses to RNA stimuli in male BXSB mice." (PMID 30199535, 2018). "Moreover, loss of TLR7 protects mice from lupus, while loss of TLR9 exacerbates the disease." (PMID 23426937, 2013). "However, other reports describe SNPs in the human TLR7 gene that associate with lupus." (PMID 22761632, 2012). "Systemic lupus erythematosus (SLE or lupus) and SjD are distinct diseases that are both characterized by heightened activation of TLR7 and TLR9 signaling networks that serve as potent modulators of chronic inflammation." (PMID 42112403, 2026). "We further demonstrate that cGAS deletion protects mice from lupus-like symptoms induced by the TLR7 agonist imiquimod (IMQ)." (PMID 41851153, 2026). "Among them, we identified pathogenic or likely pathogenic variants in genes previously associated with monogenic lupus, including a novel C1QA variant as well as other lupus-associated genes (COPA, ADAR, TLR7, IKZF3, RELA, PTPN11, SERPING1)." (PMID 41930824, 2026). "TLR7 antagonists and inhibitory anti-TLR7 monoclonal antibodies (mAbs) can protect lupus-prone NZBWF1 mice from lethal nephritis." (PMID 40910948, 2026). "Toll-like receptor 7 (TLR7), an endosomal RNA sensor, has emerged as a key contributor to lupus pathogenesis through aberrant activation." (PMID 41846847, 2026). "In preclinical models, inhibition of TLR7 or dual inhibition of TLR7/8 has been shown to ameliorate lupus nephritis in lupus-prone strains such as the New Zealand Black/New Zealand White F1 mice (NZBWF1 mice) and MRL/lpr mice." (PMID 40910948, 2026). "In this study, we revealed that TLR7 signaling activity is elevated in the spinal dorsal horn in lupus mice with thermal hyperalgesia." (PMID 41511304, 2025). "Although generally considered homologous, they paradoxically have opposing effects on lupus: TLR7 exacerbates the disease while TLR9 protects from it How they mediate opposing effects in autoimmunity remains undetermined." (PMID 40794441, 2025). "Though challenging for many reasons, this direction is compelling, as it will open new therapeutic targets to specifically promote TLR9 protective signals and/or inhibit TLR7-TIR in lupus." (PMID 40794441, 2025). "Here, we used the TLR7-driven W.Yaa model to further investigate the contribution of glutaminolysis to lupus Tfh cells comparatively to healthy controls." (PMID 40956613, 2025). "Because TLR7 expression and DC signalling are enhanced in TLR8‐deficient animals on the C57BL/6 background, lupus develops." (PMID 40976999, 2025). "The lupus mouse model induced by the Toll-like receptor 7 (TLR7) agonist IMQ effectively mimics various clinical manifestations of lupus." (PMID 40989817, 2025). "In this study, we established a lupus model in mice using IMQ, a TLR7 agonist, which is widely used in lupus research." (PMID 40989817, 2025). "In lupus‐prone mice, a deficiency in NADPH oxidase has been shown to increase TLR7 and TLR9 signaling, resulting in increased autoantibody production, which exacerbates lupus risk." (PMID 40491969, 2025).
lupus (continued). "Galectin-9 administration attenuates kidney disease severity in murine lupus models by suppressing toll-like receptor 7–mediated activation of plasmacytoid dendritic cells and B cells." (PMID 40904455, 2025). "TLR7/9-activated IRF5 elevates IL-10 in systemic lupus erythematosus (SLE) models, contrasting with its pro-inflammatory role in TLR2/4-mediated pathways." (PMID 40980176, 2025). "However, TLR9 and TLR7 have been implicated in various autoimmune diseases such as systemic lupus erythematosus (SLE) and psoriasis, suggesting that endosomal TLRs can detect self-derived NAs as indicators of cellular stress and tissue damage." (PMID 40037613, 2025). "In our model of TLR7 agonist-induced lupus, preventive supplementation with cinnamon seemed to alleviate intestinal alterations of TJ expression." (PMID 40507090, 2025). "Generation of mouse models carrying the orthologous variants has identified novel genes causing monogenic or oligogenic SLE such as TLR7, UNC93B1, SAT1 and TNIP13–6, expanding the list of monogenic lupus causes." (PMID 40386946, 2025). "Because TLR7 activation induces a lupus-like autoimmune disease, the mucosal injury and alterations reported in IMQ-treated and TLR7Tg mice are direct manifestations of the gut-associated damage resulting from the autoimmunity process." (PMID 40761803, 2025). "Remarkably, these lupus-like phenotypes were reversed when the mice were crossed with MyD88-knockout mice, highlighting the essential role of TLR7-MyD88 signaling in lupus development." (PMID 40495154, 2025). "Recently, TLR7 agonist-induced lupus has been shown to exhibit similar neuropsychiatric manifestations to spontaneous ones." (PMID 40507090, 2025). "Description of the Model: TLR7-dependent lupus models are divided into spontaneous and inducible models." (PMID 40142449, 2025). "In various autoimmune conditions including systemic lupus erythematosus and systemic sclerosis, transitional B cells produce excessive amounts of IL-6, driven by type-1 interferon and toll-like receptor-7 activation." (PMID 40259340, 2025). "In TLR7-dependent mouse lupus models, resistant starch (RS) increases SCFA production, reduces the abundance of L. reuteri, enhances ileal epithelial barrier function, and prevents translocation to distal organs." (PMID 40142449, 2025). "It has been established that overexpression of TLR7 promotes lupus-like pathology, whereas its deletion reduces it11,12." (PMID 40610751, 2025). "TLR7 activation by imiquimod, a TLR7 agonist, was the cornerstone of experimental lupus in our study." (PMID 40507090, 2025). "The immune response to these proteins can drive lupus nephritis in lupus-prone mice via TLR7 and autoimmune thrombi, respectively." (PMID 40142449, 2025). "Even though it does not appear to have a ligand, research has shown that TLR8 in mice regulates TLR7‐mediated lupus, which indicates that it is physiologically significant." (PMID 40976999, 2025). "Tlr779 mice — in which the Tlr7 TIR domain was replaced with the Tlr9 TIR domain — showed disease amelioration when compared with WT Tlr7 counterparts in the lupus-prone MRL/lpr Tlr9–/– background." (PMID 41178711, 2025). "To further verify the therapeutic effects of curcumin on LN, we established a second lupus mouse model using the TLR-7/8 agonist R848." (PMID 39053932, 2024). "Spontaneous GC formation is well described in lupus mouse models and has been shown to be either strictly dependent on B cell–intrinsic TLR7 expression or promoted upon enhanced TLR7-signaling." (PMID 38701219, 2024). "Since Tlr9 activation diminishes Tlr7-mediated pathology in the context of lupus, we next performed flow cytometry to assess expression of Tlr9 in Tlr7-deficient males and females." (PMID 39310226, 2024). "Our study shows for the first time the dysregulation of redox homeostasis and apoptosis markers in brain tissue with concomitant activation of the TLR7/MyD88 pathway in an imiquimod-induced lupus model." (PMID 39061948, 2024).
lupus (continued). "The impact of the TLR7 gene copy number in the development of lupus was further investigated using genetically engineered mice that carry varying copy numbers of the TLR7 gene (TLR7 gene dose ranged from 0 to 32 copies)." (PMID 38255243, 2024). "To determine how lupus MDSCs strengthen TLR7 pathway activation, we performed RNA-seq analysis of splenic MDSCs from 6-week-old and 24-week-old MRL/lpr mice." (PMID 38429401, 2024). "In some of these, lupus results from direct variation of TLR7 gene dose, or enhanced nucleic acid sensing function." (PMID 38866437, 2024). "Another reason we focused on TLR7 signaling was that the IMQ-induced lupus model used in this study was mediated primarily by activation of the TLR7 pathway." (PMID 38429401, 2024). "Abnormal signal transduction of TLR7 promoted systemic lupus erythematosus and Sjögren’s syndrome pathophysiological processes." (PMID 39256355, 2024). "Our study is the first to document TLR7 variation in the brain of an induced lupus model and its modulation by cinnamon supplementation." (PMID 39061948, 2024). "Enhanced TLR7 signaling is a key mechanism in lupus pathogenesis and is becoming a hotspot for research and therapy." (PMID 38866437, 2024). "Notably, TLR7 can also recognize self-derived ssRNA, with gain-of-function mutations in human TLR7 recently identified to cause both early-onset systemic lupus erythematosus (SLE) and neuromyelitis optica." (PMID 38324161, 2024). "A previous study demonstrated that paeonol, when administrated in TLR-7/8 agonist-induced lupus models, can suppress the polarization of macrophages to the M1 and promote their polarization to the M2." (PMID 39337618, 2024). "A GOF de novo mutation in TLR7 has been shown to cause human SLE and lupus nephritis." (PMID 38772735, 2024). "Excessive activation of the TLR7 pathway can aggravate lupus pathogenesis by driving the expansion of B cells and autoantibody production." (PMID 38429401, 2024). "Combined with the effect obtained on NRF2, these findings unfold the broad spectrum of cinnamon modulating activity on multiple oxidative targets, simultaneously with TLR7 attenuation in the lupus mouse hippocampus." (PMID 39061948, 2024). "A recent study indicated that enhanced TLR-7 signaling promotes aberrant survival of B cell receptor (BCR)-activated B cells, and gain-of-function genetic variations in TLR-7 can cause human lupus." (PMID 39337618, 2024). "New experimental and human data pinpoint the central position of the TLR7–MyD88 axis in lupus initiation and its blocking as a new therapeutic target." (PMID 39061948, 2024). "It is interesting to note that hydroxychloroquine, a cornerstone in lupus management, has the ability to decrease TLR7 activation by acting on endosome pH." (PMID 39061948, 2024). "B-cell-intrinsic TLR7 signalling promotes anti-RNA antibody synthesis and lupus pathogenesis in lupus-prone mice." (PMID 39062948, 2024). "In conclusion, this study demonstrated that lupus MDSCs promote TLR7 pathway activation, contributing to lupus pathogenesis through the S100A8/9-IFN-γ axis." (PMID 38429401, 2024). "In the present study, lupus MDSCs significantly promoted TLR7 pathway activation in macrophages and dendritic cells (DCs), exacerbating the imiquimod-induced lupus model." (PMID 38429401, 2024). "For example, one study of spontaneous lupus in NZB/W F1 mice demonstrated the central action of TLR7 in the brain of neuropsychiatric lupus and the benefit of its modulation." (PMID 39061948, 2024). "As in human samples, data from these experiments showed the involvement of TLR7 in the mouse lupus-like phenotype." (PMID 38831104, 2024). "A 2-fold increase in Tlr7 expression promotes autoimmunity in a lupus-prone mouse strain, while its higher expression levels induce a lupus-like autoimmune disease in a typically healthy mouse strain." (PMID 39143032, 2024).
lupus (continued). "We show that NOX2 regulates lupus by its function in macrophages/monocytes and B cells, where it modulates TLR7 signaling." (PMID 39042716, 2024). "In another group of lupus models in which Tlr7 gene expression is intact, disease pathogenesis is also dependent on TLR7 signaling." (PMID 38866437, 2024). "Previous reports have shown that VitD3 reduces TLR7 mRNA expression in PBMCs from patients with systemic lupus erythematosus and also reduces TLR8 mRNA expression in monocytes." (PMID 38839691, 2024). "For example, TLR7 is prominently involved in the immune response mechanisms of systemic lupus erythematosus (SLE) by promoting the production of type I interferons, which are crucial in the disease’s progression." (PMID 38732254, 2024). "Several murine studies further corroborate our findings, demonstrating that ABCs mediate immune dysfunction in lupus in a Tlr7-dependent manner." (PMID 39310226, 2024). "As expected, compared to B6 controls, B6.Sle1yaa mice expressed elevated levels of several lupus related genes from the Yaa locus including Tlr7." (PMID 38860651, 2024). "More importantly, the expression of MyD88 protein, a key adaptor in the TLR7 signaling pathway, was significantly enhanced in lupus mice compared to sham mice." (PMID 39061948, 2024). "Acod1−/− mice have higher levels of serum autoantibodies and kidney immune complex deposition in TLR7-induced lupus." (PMID 38605883, 2024). "It has been demonstrated that B-cell-specific knockout of Tlr7 is enough to ameliorate disease in lupus-prone mice, while B-cell-specific knockout of Tlr9 exacerbates disease." (PMID 38791389, 2024). "For instance, a novel selective Toll-like receptor 7/8 inhibitor, known as M5049, has shown potential in treating autoimmunity by blocking multiple TLR7/8 RNA ligands with significant efficacy in murine lupus models." (PMID 38732254, 2024). "Adding to the confusion, GSDMD-global knockout has previously been shown to increase myeloid cell expansion and accelerate lupus phenotypes in TLR7 agonist- or pristane-induced lupus models, which actually coincide with our phenotypic conclusions." (PMID 38831451, 2024). "TLR7, in fact, bears close association with the upregulation of IFN-α and IFN-β expression in systemic lupus erythematosus (SLE) patients." (PMID 39682695, 2024). "To address this gap, we investigated the effects of RHSL on autophagy and TLR-7 signaling, with a particular focus on their relevance to the overactive immune responses observed in lupus." (PMID 39337618, 2024). "We focused our analyses on the B cell compartment, as B cell-intrinsic Tlr7 mediates lupus pathogenesis and overexpression of Tlr9 in B cells protects against lupus." (PMID 39310226, 2024). "We then explored the regulatory effect of lupus MDSCs on the activation of bone marrow-derived macrophages (BMDMs) and dendritic cells (BMDCs) induced by the TLR7 agonist R848." (PMID 38429401, 2024). "The anti-TLR7 mAbs inhibit TLR7 responses in B cells, DCs, macrophages, and Ly6Clow patrolling monocytes and ameliorate serologic and pathologic manifestations of lupus in mice." (PMID 38255243, 2024). "In summary, lupus MDSCs can significantly promote abnormal activation of the immune system and aggravate disease progression in mice with lupus induced by the TLR7 agonist IMQ." (PMID 38429401, 2024). "The size of CL1 was augmented in lupus-prone mice compared with WT mice and was slightly increased in TLR7.tg6 compared with TLR7.tg6.Bank1–/– mice." (PMID 39163122, 2024). "TLR-7 induction with imiquimod, a topical TLR-7 agonist, is the basis of the experimental lupus model in our study: wild-type mice subjected to epicutaneous application of imiquimod cream, three times weekly, developed lupus-like manifestations." (PMID 39061948, 2024). "First, we observe increased monocytosis characterized by the selective expansion in the blood of the Ly6Clo nonclassical monocyte subset, which have been commonly reported in TLR7-driven lupus mouse models." (PMID 38701219, 2024).
lupus (continued). "Given that TLR7 plays an important role in the pathogenesis of lupus, we investigated the regulatory effects of lupus-derived MDSCs on the activation of TLR7 signaling." (PMID 38429401, 2024). "In our study, the p-FOXO3/FOXO3 ratio increased in the brain tissue of lupus mice, while cinnamon administration significantly attenuated the effect of TLR7 induction on the phosphorylation of FOXO3." (PMID 39061948, 2024). "The lupus-promoting functional consequences of enhanced TLR7 signaling result from the direct activation of the TLR7-bearing cell types." (PMID 38255243, 2024). "In mouse lupus models, TLR7/8 inhibition with M5049 (Enpatoran), a small-molecule inhibitor, demonstrated efficacy." (PMID 39143032, 2024). "We report that Bmal1, a clock gene, negatively regulates autoantibody production in a TLR-7/8-dependent model of lupus." (PMID 39664388, 2024). "Important to this model, pristane-induced lupus is female-biased and completely dependent on TLR7 activation." (PMID 38665922, 2024). "The development of Tlr7 tg mice confirmed that the Yaa gene is essential for developing an autoimmune phenotype in some spontaneous models of lupus." (PMID 38791389, 2024). "In this study, we confirmed that lupus MDSCs can promote TLR7-mediated activation of macrophages and DCs, thereby contributing to disease progression in mice with lupus induced by TLR7 agonist IMQ." (PMID 38429401, 2024). "In lupus-prone mice strains, a reduction of the TLR7 copy number from 2 to 1 abrogated the autoimmune accelerator effect." (PMID 38255243, 2024). "In our study, chronic neuroinflammation in lupus mice triggered by chronic activation of the TLR7 pathway seemed to induce an increase in Bcl-2 expression in the brain tissue as a compensatory neuroprotective mechanism against chronic oxidative stress." (PMID 39061948, 2024). "Overexpression of TLR7 can induce systemic autoimmunity in normal mice, while deletion of TLR7 can significantly alleviate the pathogenesis of lupus in mice; TLR9 deletion significantly exacerbates the pathogenesis of lupus in mice." (PMID 38429401, 2024). "The present study is the first to report that lupus MDSCs significantly promote the TLR7-mediated activation of macrophages and DCs, contributing to lupus pathogenesis." (PMID 38429401, 2024). "Taken together, these findings suggest that lupus MDSCs promote TLR7 pathway activation and lupus pathogenesis through the S100A8/9-IFN-γ axis." (PMID 38429401, 2024). "A second study examined the effects of Tlr7 ablation in Tlr8−/− female mice that develop both lupus and SD-related autoimmunity contemporaneously." (PMID 39310226, 2024). "Using BAFF-RFP reporter mice, we identified major changes in BAFF-producing cells in two mouse spontaneous lupus models (Tlr7 Tg mice and Sle1), and in a pristane-induced lupus (PIL) model." (PMID 36923413, 2023). "While we found no significant lupus-related phenotypes in CD11c-Tlr7Δ mice, even though deletion of TLR7 in cDC and pDC was highly effective, eliminating TLR7 expression in B cells had a mild effect on clinical lupus." (PMID 37606042, 2023). "Finally, corroborative work by our group revealed that TLR7 agonism accelerates both local and systemic disease in a mouse model of pSD and drives the expansion of a subset of B cells that are pathogenic in the context of lupus, termed age-associated B cells or ABCs." (PMID 39916928, 2023). "Here we used CD11c+ cell– and B cell–specific KOs of TLR7 using both the Cre-lox system and a mixed BM chimera strategy to directly test cell-specific functions of TLR7 in a mouse model of lupus that initially highlighted the role of TLR7." (PMID 37606042, 2023). "This indicated that a lupus-prone genetic background potentiates the inflammatory consequences of the activation of the TLR7/8 pathway." (PMID 37483626, 2023).